CP (ceruloplasmin)
Diseases named in the same sentence as CP in open-access papers (continued):
Sharing a sentence is not in itself a finding about the gene and the disease.
bacterial infection (9 papers, 2012 to 2025). "Despite limited data regarding ceruloplasmin activity levels in the context of bacterial infections in fish, existing analyses suggest that Y. ruckeri infection induces variable responses in ceruloplasmin concentrations." (PMID 41497472, 2025). "Nevertheless, ceruloplasmin is an acute-phase protein, which is responsive to an array of insults, such as inflammation, bacterial infection, and physical injury." (PMID 39409824, 2024). "No bacterial growth in either group was noted; the percentages of single and coinfection bacterial infections from aerobic bacteria isolated from CP and OP are presented in Table-8." (PMID 36185522, 2022). "However, the negative correlation found between CP and HP gene expressions in both studied tissues may suggest their different iron-binding properties during bacterial infection in these two tissues." (PMID 32867772, 2020).
metabolic disease (9 papers, 2016 to 2025). A congenital disorder (due to inherited enzyme abnormality) or acquired (due to failure of a metabolically important organ) disorder resulting from an abnormal metabolic process. "ACP must be distinguished from other metabolic disorders that cause an abnormal increase in ferritin levels and/or a decrease in CP levels." (PMID 40082989, 2025). "This study revealed the hypoglycemic and hepatoprotective effect of CP by regulating gut microbiota composition and PPARα subcellular localization, highlighting its potential for therapeutic candidate for metabolic disorders." (PMID 38831430, 2024). "Serum values of AST, ALT, α1-antitrypsin, copper, ceruloplasmin, thyroid hormones, sweat chloride, and screening biochemistries for metabolic diseases were within the normal range." (PMID 36274106, 2023). "However, the relationship between CP as an acute-phase protein with pro-inflammatory activity, and metabolic diseases, has also been demonstrated, including in its role in the development of diabetes, obesity, hyperlipidemia, and other cardiovascular diseases." (PMID 40990027, 2025).
heart disease (6 papers, 2018 to 2025). "Ceruloplasmin is secreted by the liver and activated monocytes and elevated levels of ceruloplasmin in the blood are risk factors for several cardiac diseases." (PMID 37047306, 2023). "Greater efforts are needed to understand whether elevated circulating CP plays a causative and pathogenic role in heart disease and the associated molecular mechanisms." (PMID 35277059, 2022). "Thus, copper deficiency that reduces CP oxidative activity may indirectly impact heart disease via dysregulation of iron homeostasis." (PMID 35277059, 2022). "The observed resistance to high-fat diet–induced lipid accumulation in CP-Tg mouse liver further demonstrated the possible long-term benefits of the prevention of heart diseases by controlling the microenvironment of cellular AA metabolism in favor of PGI2 using the COX-1-10aa-PGIS gene." (PMID 29374184, 2018).
kidney disease (5 papers, 2021 to 2024). "In contrast to mutations in AP convertase components, the causative role of mutations in their CP/LP counterparts in the course of complement-mediated renal diseases is not straightforward." (PMID 34899688, 2021).
infectious disease (4 papers, 2015 to 2023). A disorder directly resulting from the presence and activity of a microbial, viral, or parasitic agent in humans. "The role of Cu in the acute-phase protein ceruloplasmin in controlling acute inflammatory-infectious disorders, leading to a marked increase in Cu serum concentrations, is well known in both dogs and humans." (PMID 32570865, 2020).
retinopathy (3 papers, 2020 to 2022). "Some studies showed higher levels of plasma uric acid and ceruloplasmin in diabetic foot patients with retinopathy." (PMID 32831070, 2020). "However, the reasoning that levels of serum ceruloplasmin would rise with increasing severity of retinopathy because of the presumed increase in anti-oxidant activity was not corroborated by this study." (PMID 33680612, 2021). "In the present study, there was no statistical difference in serum levels of ceruloplasmin among diabetic patients without retinopathy as compared to those with DR." (PMID 33680612, 2021).
psychiatric disorder (2 papers, 2020 to 2024). A disorder characterized by behavioral and/or psychological abnormalities, often accompanied by physical symptoms. "In light of the relationship between ceruloplasmin, PD, and psychiatric disorders associated with dopamine dysregulation, the present study aimed to determine whether there was an association between serum ceruloplasmin levels and impulsivity." (PMID 33062249, 2020). "Elevated levels of CP in the bloodstream have been observed in individuals with other psychiatric disorders." (PMID 38646205, 2024).
brain diseases (1 paper, 2018). "More broadly, CP-AMPAR-mediated Ca2+ signaling has been implicated in the pathophysiology of several brain diseases." (PMID 30618708, 2018).
eye problems (1 paper, 2024). "Interestingly, only 10% of the male CP mice (1/10) developed eye problems, supporting a sex-dependent phenotype." (PMID 38335300, 2024).
immune disease (1 paper, 2020). "The data presented show that three of seven proteins (ceruloplasmin, Complement C3 and Complement C6) are functionally implicated in immune disease and inflammatory response, DNA replication and cellular assembly and organization." (PMID 32620920, 2020).
inflammation (1 paper, 2013). Aberrant reaction of the microcirculation characterized by movement of fluid and leukocytes from the blood into extravascular tissues. "The ease of determining serum CP levels and its reliable correlation with liver inflammation and fibrosis in male patients suggests that using CP as a biomarker for fibrosis could potentially reduce the need for liver biopsies." (PMID 24282481, 2013).
peripheral neuropathies (1 paper, 2015). "In order to confirm that the environment of CSF from PD patients can promote ceruloplasmin modifications, we added purified ceruloplasmin to the CSF of healthy subjects (H) or patients with peripheral neuropathies (PN) or PD, and analysed it before and after incubation for different times." (PMID 26537957, 2015).
vasculopathy (1 paper, 2013). "CP is a player in inflammation, coagulation, angiogenesis, and vasculopathy, but its role in the pathogenesis of acute rejection is unknown." (PMID 23592955, 2013).
CP also shares sentences with these, for which no sentence is quoted: liver (6 papers); renal failure (5); Brain atrophy (4); Protein-losing enteropathy (4); adenocarcinoma (3); autosomal recessive inherited disease (3); gingivitis (3); neutropenia (3); acute myeloid leukaemia (2); Atopic Dermatitis (2); autoimmune disease (2); Congenital cataracts (2); copper metabolism disorder (2); cryptogenic cirrhosis (2); Dystonia (2); Encephalopathy (2); epileptic seizure (2); Huntington disease (2); intrahepatic cholestasis (2); legionellosis (2); lung squamous cell carcinoma (2); microcytic anemia (2); movement disorder (2); Myeloma (2); obsessive-compulsive disorder (2); occipital horn syndrome (2); Opportunistic infection (2); psychological distress (2); pulmonary fibrosis (2); pulmonary tuberculosis (2).
A further 150 diseases each share a sentence with CP in 2 papers or fewer.